RNU1-75P (RNA, U1 small nuclear 75, pseudogene)
Gene: Small nuclear RNA gene on chromosome 1 (119,331,397 to 119,331,525, reverse strand). Ensembl gene ENSG00000194297.
Homologues: Orthologues: macaque U1 (91% identical), chimpanzee U1 (90% identical), rabbit U1 (66% identical), mouse Gm55339 (60% identical), rat LOC120093368 (58% identical). Paralogues in human: RNU1-1 (78% identical), RNU1-2 (78% identical), RNU1-27P (78% identical), RNU1-28P (78% identical), RNU1-3 (78% identical), RNU1-4 (78% identical), RNVU1-18 (78% identical), RNVU1-29 (78% identical), RNVU1-7 (78% identical), U1 (78% identical), RNVU1-28 (77% identical), RNU1-39P (76% identical), and 133 more.